ASTN2 (astrotactin 2)
Diseases named in the same sentence as ASTN2 in open-access papers:
ASTN2 is named in the same sentence as 53 diseases in open-access papers, as found by Europe PMC text mining. Sharing a sentence is not in itself a finding about the gene and the disease. The quoted sentences say what the papers report.
migraine (13 papers, 2014 to 2026). "ASTN2 has also been associated with migraines and chronic pain- an area known to correlate strongly with mental health." (PMID 34440368, 2021). "Earlier research reported that genetic variants within or near the ASTN2 gene are associated with neuropsychiatric conditions such as schizophrenia, autism, and cognitive dysfunction, making it a potential candidate for both migraine and glycemic traits." (PMID 36808568, 2023). "Biologically, implicated loci suggest contributions from both neuronal circuit organisation (ASTN2) and telomere and vascular maintenance pathways (CTC1), supporting a broader neurovascular model of migraine susceptibility." (PMID 42194998, 2026). "In our study, substantially elevated SNP-based heritability and replicable top hits in risk loci of PRDM16, FHL5, ASTN2, STAT6/LRP1, SLC24A3 genes were found among migraine-first patients." (PMID 39333847, 2024). "Among these shared genomic regions, those on chromosomes 1 and 9 harbour the MEF2D and ASTN2 genes, previously reported to be the closest genes to a lead migraine SNP and headache SNP." (PMID 36808568, 2023). "A subsequent Chinese replication study of 581 migraine cases and 533 ethnically matched controls identified three risk loci rs2274316 (MEF2D), rs6478241 (ASTN2) and rs2651899 (PRDM16) previously identified in European samples." (PMID 37245199, 2023). "The four regulatory regions include a CpG island located near the PHACTR1 migraine risk locus and three PREs located near the KCNK5, ASTN2, and RNF213 migraine risk locus." (PMID 32076896, 2020). "Furthermore, the subtype analysis in this meta-analysis concluded that migraine without aura (MO) was significantly associated with seven genetic loci: near TSPAN2, TRPM8, PHACTR1, FHL5, ASTN2, FGF6, and LRP1." (PMID 39850553, 2024). "Whereas seven loci (i.e. near TSPAN2, TRPM8, PHACTR1, FHL5, ASTN2, near FGF6, and LRP1) were associated with migraine without aura (in a sample of 8348 cases and 139,622 controls), none were associated with migraine with aura (6332 cases vs. 144,883 controls)." (PMID 32503413, 2020). "Recently, genome-wide studies have provided new insights for genes associated with migraine disease (the ion channel gene, TRPM8, FHL5, ASTN2, and LRP1 but UTS2 gene was not one of them." (PMID 27090416, 2016). "Second, some SNPs show no selectivity (i.e. “basic” model) for migraine attack frequency ≥6/year but selectivity (i.e. “subset” or “inverse subset” models) for other characteristics, for example aura status (rs11172113 [LRP1], rs6478241 [ASTN2], rs13208321 [FLH5], rs10504861 [near MMP16])." (PMID 24852292, 2014).
schizophrenia (12 papers, 2009 to 2025). A major psychotic disorder characterized by abnormalities in the perception or expression of reality. "Disruption of ASTN2 is considered a risk factor for these neurodevelopmental disorders, including schizophrenia, bipolar disorder, autism spectrum disorder, and ADHD." (PMID 41009966, 2025). "Deletions of ASTN2 have been associated with schizophrenia and other psychiatric and neurodevelopmental disorders." (PMID 34294844, 2021). "Examples of diagnostic-biased genes include GRIA4 (glutamate receptor, inotropic, AMPA4) and ASTN2 (astrotactin 2), both of these genes have been previously implicated in schizophrenia." (PMID 25206360, 2014). "Interestingly, SNPs within ASTN2 have been associated with cognitive decline and reduced hippocampal volume and several psychiatric conditions such as schizophrenia, ADHD, and bipolar disorder." (PMID 30112632, 2019). "Deletions involving ASTN2 have been identified in patients with schizophrenia, bipolar disorder, and autism spectrum disorder in copy number variant (CNV) analyses." (PMID 41009966, 2025). "ASTN2 deletions has been identified in patients with ASD, ADHD, and schizophrenia, highlighting how ASTN2 alterations are a risk factors for NDDs." (PMID 38674362, 2024). "With psychiatric traits, ASTN2 has been associated with a range of conditions—bipolar, depression, autism, ADHD and schizophrenia." (PMID 34440368, 2021). "Three SNPs, rs955302 (β^G×ε4*=4.0,p=0.01), rs4837254 (β^G×ε4*=2.3,p=0.04) and rs12342331 (β^G×ε4*=2.1,p=0.04), are located at the intergenic region between ASTN2 and TLR4 at Chromosome 9 and are 400k, 430k, and 492k downstream of rs1360695 associated with Schizophrenia." (PMID 30133451, 2018). "In addition to novel GWS loci, we have identified a significant genetic correlation with schizophrenia and association of ASD with several neurodevelopmental-related genes such as EXT1, ASTN2, MACROD2, and HDAC4." (PMID 28540026, 2017). "We identified a number of genes with significant epigenetic alterations in schizophrenia, and some of these genes, such as GRIA4, ASTN2, and DCDC2 (doublecortin domain containing 2) with increased DNA methylation at particular CpG loci, have previously been implicated in schizophrenia." (PMID 25206360, 2014). "ASTN2 is a neuronal adhesion-related gene, associated with Schizophrenia, the ASTN2 association with TG was not reported before this study, although ASTN2 gene SNPs were nominally associated with total cholesterol and LDL in a GWAS for lipid phenotypes in the Framingham Heart Study." (PMID 26308950, 2015).
autism spectrum disorder (8 papers, 2010 to 2025). A spectrum of developmental disorders that includes autism, and Asperger syndrome. "Some studies have demonstrated that the ASTN2 gene played an important role in glial-guided neuronal migration and mutated in neurodevelopmental disorders, including intellectual disability and autism spectrum disorders." (PMID 36358398, 2022). "Deletion of ASTN2 has been associated with SCZ, and CNV of this gene was recently found in patients with autism spectrum disorders (ASD)." (PMID 21048971, 2010). "In addition to hosting rare copy number variants (CNV) that have been linked to autistic spectrum disorders, ADHD, and OCD by a large GWAS, this locus also contains the astroactin-2 (ASTN2) and tri-component motif protein 32 (TRIM32)." (PMID 34201295, 2021). "ASTN2, another gene which interacts with GCNT1, also has demonstrated associations with neural phenotypes including attention-deficit/hyperactivity disorder (ADHD), autism spectrum disorders (ASD), neuronal development, and Alzheimer's disease." (PMID 32915819, 2020).
autism (6 papers, 2011 to 2024). Persistent deficits in social interaction and communication and interaction as well as a markedly restricted repertoire of activity and interest as well as repetitive patterns of behavior. "The top-ranked clique in our analysis (hereafter will be referred as Clique I), was delineated by the autism genes: Ptchd1, Galnt13, Dpp6 and Astn2, and included another 29 genes, inter-connected with a co-expression values of ≥70%." (PMID 23935468, 2013). "The second top-ranked clique (hereafter will be referred as Clique II) included the autism genes: Rims3, and Astn2, and another four genes, all inter-connected at ≥79% co-expression level." (PMID 23935468, 2013).
Obesity (4 papers, 2018 to 2023). Accumulation of substantial excess body fat. "In humans,the ASTN2 gene is associated with the level of triglycerides inthe blood and the development of obesity." (PMID 37867610, 2023). "Overall, a number of interesting genes that could play a role in obesity susceptibility have been identified within these CNVs (e.g. ASTN2, APOA2, PARK2, LINGO2, PLCB1, PTEN, and CIDEA)." (PMID 29441128, 2018). "In silico analyses provide support for the central obesity signal acting through ASTN2, however most of the other signals are likely acting through other genes in the locus." (PMID 34440368, 2021). "Notably, a pathway analysis demonstrated a connection between ASTN2 and plasma triglycerides which further suggested the possible influence on neuronal pathways and insulin sensitivity, contributing to obesity and T2D." (PMID 34440368, 2021).
bipolar disorder (3 papers, 2019 to 2025). A disorder of the brain that causes unusual shifts in mood, energy, activity levels and the ability to carry out day-to-day tasks. "Among the four sex-specific loci identified in the current study, two, PBRM1 and ASTN2, have been involved in susceptibility to bipolar disorder and other psychiatric phenotypes." (PMID 34294844, 2021).
depression (3 papers, 2016 to 2023). "Psychiatric associations with ASTN2 single nucleotide polymorphisms (SNPs) include those with bipolar disorder (BPD), major depressive disorder (MDD), and response to anti-psychotic treatment." (PMID 34440368, 2021). "Case K, the other individual with an ASTN2 deletion, has depression, ADHD, and Tourette syndrome." (PMID 27777633, 2016).
Intellectual disability (3 papers, 2022 to 2023). "In recent studies on ASTN2 and general happiness, although very limited, copy number variants of ASTN2, both deletions and duplications, have been identified in patients with neurodevelopmental disorders, including ASD, SCZ, ADHD, BD, intellectual disability, and global developmental delay." (PMID 36672898, 2023).
breast carcinoma (2 papers, 2018 to 2020). "The EEC genes identified in here (with the exception of AGPAT3/4, ASTN2, and EEA1), have previously been shown to be associated with breast cancer in gene expression and functional studies." (PMID 29965997, 2018).
Cognitive impairment (2 papers, 2021 to 2023). Abnormal cognition is characterized by deficits in thinking, reasoning, or remembering. "The longest deletion (336 kb del) includes a large portion of the ASTN2 gene, and the patient with this deletion shows mild progressive cognitive impairment in addition to LGMD R8 symptoms." (PMID 37217920, 2023). "This discrepancy in phenotypes suggests that cognitive impairment should be associated with ASTN2 loss of function rather than TRIM32 loss of function." (PMID 33485293, 2021).
diabetes (2 papers, 2023 to 2025). "Furthermore, a number of genes in this set (Peak1, Astn2, Bcar1, Ctnnal1, Ppfibp2) is associated with significant diabetes-related risk loci." (PMID 40667025, 2025). "It is worth noting that the roles of PTPRN2, ASTN2, GRIN1, SLC6A18, and PDE2A in influencing FPG levels or diabetes had previously been suggested." (PMID 37461060, 2023).
chronic myelogenous leukemia (1 paper, 2021). "For instance, BCR-ABL in chronic myelogenous leukemia (CML), TMPRSS2-ETS, SLC45A3-ELK4, and D2HGDH-GAL3ST2 in prostate cancer, LHX6-NDUFA8 and SLC2A11-MIF in cervical cancer, RRM2-C2orf48 in colorectal cancer (CRC), and ASTN2-PAPPAas in esophageal cancer." (PMID 33805149, 2021).
conductive hearing loss (1 paper, 2025). "Considering that it is recognized that common middle ear disorders often can result in conductive hearing loss, these findings suggest that ASTN2 may represent a novel candidate involved in the underlying mechanisms of such conditions." (PMID 40458558, 2025).
endometriosis (1 paper, 2014). The growth of functional endometrial tissue in anatomic sites outside the uterine body. "Two SNPs within the 22 CNVRs show significant genotypic association with endometriosis after adjusting for multiple testing; rs758316 in DPP6 on 7q36.2 (P = 0.0045) and rs4837864 in ASTN2 on 9q33.1 (P = 0.0002)." (PMID 25083881, 2014).
glioblastoma (1 paper, 2022). The most malignant astrocytic tumor (WHO grade IV). "Eventually, a western blot assay and a wound-healing assay first confirmed that ASTN2 expression in glioblastoma cell lines is higher than that in normal human astrocytes and affects the migration ability of glioblastoma cells, making it a potential therapeutic target." (PMID 36358398, 2022). "Although some studies have demonstrated that ASTN2 plays an important role in glial-guided neuronal migration, there are no studies about its impact on glioblastoma cell migration." (PMID 36358398, 2022).
glioma (1 paper, 2022). A benign or malignant brain and spinal cord tumor that arises from glial cells (astrocytes, oligodendrocytes, ependymal cells). "We found for the first time that the down-regulation of ASTN2 could inhibit the migration of GBM LN229 and A172 cell lines, which provides a new direction for future studies on the inhibition of glioma migration and metastasis." (PMID 36358398, 2022).
hip fracture (1 paper, 2019). Traumatic or pathological injury to the hip in which the continuity of either the femoral head, femoral neck, intertrochanteric or subtrochanteric regions is broken. "And more specifically, a GWAS meta-analysis for hip shape was published very recently and found 17q24.3 and ASTN2 as associated in lookups in hip fracture GWAS (unpublished data)." (PMID 31231309, 2019).
Leukoencephalopathy (1 paper, 2025). This term describes abnormality of the white matter of the cerebrum resulting from damage to the myelin sheaths of nerve cells. "Several genome-wide association studies (GWAS) have identified single-nucleotide polymorphisms (SNPs) in the following genes: TRIO, PRKG1, ANK1, COL4A2, NTN1, and ASTN2 that were associated with increased risk of MTX-induced neurotoxicity and leukoencephalopathy on imaging in patients with ALL." (PMID 41029358, 2025).
metabolic syndrome (1 paper, 2015). A cluster of metabolic risk factors for CARDIOVASCULAR DISEASES and TYPE 2 DIABETES MELLITUS. "A previous linkage analysis for lipid-related latent gene-expression quantitative traits with metabolic syndrome found that ASTN2 was associated with lipid levels." (PMID 26308950, 2015).
uterine disorder (1 paper, 2024). A non-neoplastic or neoplastic disorder that affects the uterine corpus or the cervix. "The uterine disorders cluster (two) was significantly associated with six loci, WNT4, GREB1, BSN, SYNE1, GDAP1, and ASTN2." (PMID 39315247, 2024).
neurodevelopmental disorder (11 papers, 2016 to 2025). A behavioral and cognitive disorder with onset during the developmental period that involves impaired or aberrant development of intellectual, motor, or social functions. "ASTN2, which primarily encodes astrotactin, has been reported to be dysregulated in various neurodevelopmental disorders." (PMID 36358398, 2022). "Genetic variation at the human BRINP2/ASTN1 and BRINP1/ASTN2 loci has been implicated in neurodevelopmental disorders." (PMID 27826231, 2016). "In addition to including the entire TRIM32 gene, all 7 deletions also include part of the ASTN2 gene, which encodes astrotactin 2, a brain protein that may be involved in neuronal migration and is associated with neurodevelopmental disorders." (PMID 37217920, 2023). "The associated SNPs map at the highly conserved ASTN2/BRINP1 locus at chr9q33.1–33.2, which contains five genes (ASTN2, BRINP1, TRIM32, TLR4 and C5) that have been previously associated with neurodevelopmental disorders (reviewed in29)." (PMID 34267256, 2021). "In a recent study of 89,985 individuals, approximately 71% of whom were reported to have a neurodevelopmental disorder (NDD), a total of 46 deletions and 12 duplication mutations were observed in the ASTN2 gene." (PMID 28540026, 2017).
psychiatric disorder (5 papers, 2015 to 2024). A disorder characterized by behavioral and/or psychological abnormalities, often accompanied by physical symptoms. "Our research group identified the variant in ASTN2 as one of the candidate risk factors across these psychiatric disorders by whole-genome copy number variation analysis." (PMID 38830862, 2024). "Based on the findings of these previous reports and those of the present study, further research on mitochondria is needed to better understand the underlying mechanisms of psychiatric disorders based on ASTN2 deletion." (PMID 38830862, 2024). "Recently, we identified the variants in ASTN2 as a candidate risk factor for psychiatric disorders by whole-genome copy number variation (CNV) analysis." (PMID 38830862, 2024). "In this study, we showed how ASTN2 deletion, a candidate cross-disorder risk variant for psychiatric disorders, affects human neuronal cells." (PMID 38830862, 2024). "Our results suggest that as a pathogenic mechanism for psychiatric disorders, ASTN2 deletion promotes mitophagy by downregulating ZNF558 expression in human neuronal cells." (PMID 38830862, 2024). "First, variants of ASTN2 have been identified in several psychiatric disorders such as SCZ, ASD, and BP." (PMID 38830862, 2024). "Our results suggest that ASTN2 deletion is related to the common pathogenic mechanism of psychiatric disorders by regulating mitophagy via ZNF558." (PMID 38830862, 2024). "ASTN2 is also widely proven to be associated with a number of mental illnesses in humans and has exhibited a relationship with hippocampus volume." (PMID 36163035, 2022). "Our research group recently identified heterozygous ASTN2 deletions in eight patients with psychiatric disorders (three patients with SCZ, one patient with ASD, and four patients with BP) by a whole-genome CNV analysis." (PMID 38830862, 2024). "Interestingly, NCAM1, ASTN2, and PDE4B are known to play important roles in regulating synaptic function and are implicated in human psychiatric disease." (PMID 26694817, 2015).
cancer (1 paper, 2013). A tumor composed of atypical neoplastic, often pleomorphic cells that invade other tissues. "However, we found conspicuously higher expression of 2 chimeras, namely ASTN2-PAPPA and GOLM1-MAK10, in patients' cancer tissue vs. matched benign tissue, as well as in ESCC cancer cell lines vs. immortalized esophageal cells." (PMID 24243830, 2013).
ASTN2 also shares sentences with these, for which no sentence is quoted: Alzheimer disease (3 papers); Anxiety (3); esophageal cancer (3); prostate carcinoma (3); attention deficit-hyperactivity disorder (2); Bladder cancer (2); cervical cancer (2); colorectal cancer (2); developmental delay (2); epilepsy (2); esophageal squamous cell carcinoma (2); Anorexia (1); central obesity (1); cognitive decline (1); emphysema (1); fibromyalgia (1); gastric cancer (1); Headache (1); learning disability (1); lung adenocarcinoma (1); male pattern baldness (1); microcephaly (1); middle ear disorder (1); migraine without aura (1); non-small cell lung carcinoma (1); Parkinson disease (1); pulmonary diseases (1); speech-language delay (1); Tourette syndrome (1); tumor (1).